SOCS3 (suppressor of cytokine signaling 3)
Diseases named in the same sentence as SOCS3 in open-access papers (continued):
Sharing a sentence is not in itself a finding about the gene and the disease.
lung carcinoma (36 papers, 2007 to 2025). "Moreover, in lung cancer, a reduction in SOCS3 enhances the expression of STAT3 thus causing the progression of cancer cells." (PMID 31569687, 2019). "For example, Grivennikov and Karin reported that autocrine IL-6 as an important activator of oncogenic STAT3 was implicated in lung adenocarcinomas; furthermore, SOCS3 has been found to be suppressed by hypermethylation in lung cancer cells, which promoted the progression of lung cancer." (PMID 28591704, 2017). "Using a complementary Kras-driven model of lung cancer, we found that the glycolytic shift in AMs correlates with a marked reduction in SOCS3 secretion." (PMID 41567211, 2025). "Together, our results indicate that joint PARP7 inhibition and SOCS3 deletion lead to enhanced lung cancer growth suppression." (PMID 40493189, 2025). "In a KrasG12D mutant mouse model of lung cancer, we found that AMs isolated from tumor-bearing lungs exhibited increased glucose uptake, which inversely correlated with SOCS3 secretion." (PMID 41567211, 2025). "Such a parallel not only supports the translational significance of our study but also underscores the potential for targeting metabolic pathways to modulate SOCS3 secretion therapeutically in human lung cancer." (PMID 41567211, 2025). "Downregulation of SOCS3 expression was associated with the TNM stage and poor prognosis of patients with lung cancer." (PMID 35884544, 2022). "High methylation of the SOCS3 promoter has been reported in several cancers, such as lung cancer and hepatocellular and cervical carcinomas." (PMID 34691358, 2021). "The methylation status of the SOCS3 promoter in EML4-ALK-positive H2228 lung cancer cells and lung cancer tissues was detected by methylation-specific PCR (MSP) analysis and verified by DNA sequencing." (PMID 27666544, 2016). "MSP and DNA sequencing assay results indicated the presence of SOCS3 promoter methylation in H2228 cells as well as in three cases of seven EML4-ALK-positive lung cancer tissues." (PMID 27666544, 2016). "SOCS3 gene has been found to be silenced by promotor methylation in human lung cancer, and restoration of SOCS3 suppresses cell growth and promotes cell apoptosis, indicating that increase in SOCS3 signaling enhances apoptosis." (PMID 26982332, 2016). "Secondly, methylation in CpG islands within this region has been shown to be associated with SOCS3 silencing and aberrant activation of JAK/STAT signalling in lung cancer cell lines, and hence biologically relevant." (PMID 24131863, 2013). "Frequent hypermethylation in the CpG islands of the functional SOCS3 promoter has been found in lung-cancer tissue samples to correlate with its transcription silencing." (PMID 20628618, 2010). "Restoration of suppressors of cytokine signalling-3 (SOCS-3), which is frequently silenced by hypermethylation in lung cancer cells, resulted in the down-regulation of activated STAT3, leading to induction of apoptosis and growth suppression." (PMID 17683579, 2007). "Furthermore, in lung cancer cells, the suppressor of cytokine signaling 3 (SOCS3) mediates in NOD2 ubiquitination, which results in proteasomal decomposition." (PMID 41340462, 2025). "Moreover, their results revealed that drug-sensitive lung cancer cells obtained gemcitabine resistance after taking up exosomal miR-222-3p, whose target gene was proven to be suppressor of cytokine signaling 3 (SOCS3)." (PMID 31728212, 2019). "Moreover, another study indicated that SOCS3 was silenced by hypermethylation in lung cancer, which further promoted the progression of lung cancer." (PMID 28591704, 2017).
lung carcinoma (continued). "Although various oncogenic targets have been described to account for the potent anticancer activities of BSN, our study is the first one to explore the effects of BSN both on STAT3 signaling pathway and on the negative regulators of STAT3 signaling (PIAS-3 and SOCS-3) in human lung carcinoma." (PMID 25788267, 2015). "A previous study has confirmed that SOCS3 may significantly inhibit the proliferation of lung cancer cells in vitro and indicated that SOCS3 may act as an anti-oncogene involved in the development of tumors." (PMID 25695729, 2015). "SOCS3 is also silenced by hypermethylation in a human lung cancer cell line." (PMID 19698101, 2009). "The results indicated that the expression of SOCS3 mRNA was upregulated in lymphoma, esophageal cancer, and glioma compared with normal tissues, while the expression of SOCS3 mRNA was downregulated in bladder cancer, lung cancer, leukemia, and sarcoma compared with the respective normal controls." (PMID 35600392, 2022). "Moreover, the precise role of SOCS3 in regulating migration-associated cytoskeleton proteins downstream of PYK2 has not been characterized in relation to lung cancer metastasis." (PMID 18507841, 2008). "Studies of SOCS3 may foster new anti-chemotactic approaches to suppress lung cancer metastasis." (PMID 18507841, 2008). "However, little is known about whether SOCS3 could regulate PYK2 pro-migratory function in lung cancer." (PMID 18507841, 2008). "At the same time, lung cancer cells often downregulate STAT3 inhibitor SOCS3 which exacerbates the IL-6/STAT3 loop; overexpression of SOCS3 and PIAS can restore normal tumor suppression ability." (PMID 35406557, 2022). "MiR-410 down-regulation increases the expression of SOCS3 leading to the decreased level of STAT3 protein and minimized progression of lung cancer cells." (PMID 31569687, 2019). "Co-expression analysis revealed that ACSL1 was coexpressed with MYBPH, PTPRE, PFKFB3, SOCS3 in colon cancer and with LRRFIP1, TSC22D1 in lung cancer." (PMID 27171439, 2016). "The aim of this study is to investigate the methylation status of the SOCS3 promoter in EML4-ALK-positive H2228 cells and lung cancer tissues." (PMID 27666544, 2016). "Osimertinib exposure leads to an upregulation of suppressor of cytokine signaling 3 (SOCS3), which competes with NRF2 for KEAP1 binding, diminishing NRF2 degradation, activating antioxidant pathways, and contributing to osimertinib resistance in lung cancer." (PMID 38982494, 2024). "In addition, SOCS3, A20 (TNFIAP3), and CYLD, the transcriptional targets of STAT3 and RelA, were increased in the lung macrophages of mice with lung cancers." (PMID 33539325, 2021). "Interestingly enough, SOCS3 is known to mediate the JAK/STAT3 signaling pathway to regulate cell proliferation, differentiation, and apoptosis in lung cancer." (PMID 31130822, 2019). "The aerrant methylation of the SOCS3 promoter region in EML4-ALK (+) H2228 cells and lung cancer tissues may be significantly involved in the pathogenesis of EML4-ALK-positive lung cancer." (PMID 27666544, 2016). "Our analyses reveal that AMs from both mouse models of lung cancer and human NSCLC patients exhibit similar enrichment of glycolytic and non-canonical TCA cycle gene signatures, alongside reduced SOCS3 secretion." (PMID 41567211, 2025).
melanoma (32 papers, 2010 to 2025). A malignant, usually aggressive tumor composed of atypical, neoplastic melanocytes. "SOCS1 and SOCS3 are key players also implicated in melanoma cell growth and tumor development, even if controversial effects have been described." (PMID 38975347, 2024). "Both NQO1 and SOCS3 are associated with lower malignancy grade in melanoma." (PMID 37894348, 2023). "In murine models of melanoma as well as lung and ovarian cancers, tumor-associated DCs exhibited an increased expression of the suppressor of cytokine signaling-3 (SOCS3), which suppressed the activity of the pyruvate kinase M2 (PKM2) enzyme responsible for catalyzing the final step of glycolysis." (PMID 34413487, 2022). "Together, these data suggest that SOCS3 expression may be associated with more metastatic or aggressive melanoma tumors." (PMID 20398276, 2010). "Similarly, IL-10 is known to promote Socs3 gene expression, and melanoma-associated DC have been found to exhibit SOCS3-mediated inhibition of the M2 pyruvate kinase (PKM2) that catalyzes conversion of phosphoenolpyruvate into pyruvate in the final step of glycolysis." (PMID 29209327, 2017). "The interaction between melanoma cells and microglia supports BM progression through melanoma-derived IL-6, which enhances STAT3 phosphorylation and SOCS3 expression in microglia, thereby aiding melanoma cell survival." (PMID 40076927, 2025). "The repression of SOCS3 in malignant melanoma cells contributes to anti-apoptotic mechanisms and accelerates cell proliferation, suggesting that constitutive SOCS3 expression confers a proliferative advantage to human melanoma cells." (PMID 38975347, 2024). "Consistently, the targeted inhibition of SOCS3 activity in macrophages determined the suppression of melanoma metastasis and prolonged survival in mice xenografted with B16F10 cells." (PMID 38975347, 2024). "In contrast to its immunosuppressive effect in macrophages and microglia cells, SOCS3 has a protective, anti-tumor role in melanoma." (PMID 37894348, 2023). "SOCS3 overexpression in microglia cells evoked microglial support in melanoma brain metastasis by increasing melanoma cell migration and proliferation." (PMID 37296634, 2023). "SOCS3 also promotes melanoma progression and attenuates the therapeutic efficacy of IFN-α and IFN-γ treatments." (PMID 35226171, 2023). "The upregulated expression of SOCS3 in microglia treated with MCM from the four melanoma cell lines was validated by RT-qPCR." (PMID 37296634, 2023). "We next asked if physical contact (by co-culturing) of microglia cells with the melanoma cells would also upregulate SOCS3 expression." (PMID 37296634, 2023). "In view of its important role in cancer biology, we asked if microglial SOCS3 is functionally involved in the melanoma-microglia crosstalk." (PMID 37296634, 2023). "On the other hand, Cutaneous T-Cell Lymphoma (CTCL) and melanoma cells express a high level of SOCS-3, which protects malignant cells from cytokine-mediated antitumor effect, e.g., IFN-α." (PMID 35226171, 2023). "The use of confocal microscopy also validated the upregulated protein expression of SOCS3 in microglia treated for 4 h with MCM of all four melanoma cell lines." (PMID 37296634, 2023). "Microglia cells showed significantly higher mRNA expression for JAK1, STAT3, and SOCS3 compared to melanoma cells." (PMID 37296634, 2023). "Gene knockout phenotype analysis of CRISPR screening indicated that SOCS3-knockout was a significant influencing factor of lymphocyte-mediated tumor killing in B16 melanoma (Freeman_2019_NK) and MC38 colon cancer (Kearney2018_T_PD1) models." (PMID 35600392, 2022). "CCR5 blockade decreased the percentage of MDSCs and inhibited melanoma proliferation, mainly through upregulating suppressor of cytokine signaling 3 (SOCS3) expression, which in turn inhibited the IL-STAT3 pathway." (PMID 34527668, 2021).
melanoma (continued). "Genes of special interest previously associated with various types of cancer where the SMAD6 and SOCS3 genes coupled to aggressive kidney cancer, and the MX2 gene with suggested role in melanoma pathogenesis." (PMID 30642274, 2019). "In the tumor-bearing mice, the expression of SOCS3 was increased after 14 days of melanoma implantation." (PMID 30555329, 2018). "SOCS3 also promotes the progression of melanoma and attenuates the therapeutic efficacy of IFN-α and IFN-γ treatments." (PMID 28228755, 2017). "Melanoma cells abnormally express high levels of SOCS3, which influences the responsiveness of melanoma cells to IFN-α and IFN-γ and consequently reduces the efficiency of immunotherapy." (PMID 28228755, 2017). "Epigenetic inactivation of SOCS3 was reported in human malignant melanomas and glioblastoma multiforme." (PMID 26482433, 2015). "SOCS3 is methylated in approximately 90% of head and neck squamous cell carcinoma samples, 74% of oesophageal Barrett's adenocarcinomas, 60% of melanomas, in HCC, and in nonsmall cell lung carcinomas." (PMID 24757565, 2014). "SOCS1 and SOCS3 proteins were expressed at basal levels in melanocytes and in all melanoma cell lines examined." (PMID 20398276, 2010). "The present data suggest that SOCS1 and SOCS3 proteins represent a means by which melanoma cells can evade the direct effects of IFN-α and IFN-γ." (PMID 20398276, 2010). "For example, IFN-α and IFN-γ induced SOCS3 protein expression in the A375 melanoma cell line while both SOCS1 and SOCS3 proteins were upregulated in the HT144 cell line." (PMID 20398276, 2010). "Conversely, siRNA inhibition of SOCS1 and SOCS3 expression in melanoma cells enhanced their responsiveness to interferon stimulation." (PMID 20398276, 2010). "Conversely siRNA-mediated inhibition of SOCS1 and SOCS3 expression enhanced the interferon-responsiveness of human melanoma cells." (PMID 20398276, 2010). "Expression of SOCS1 and SOCS3 has been reported in melanoma cell lines and in surgical specimens obtained from malignant melanoma patients where it indicates a poor-prognosis." (PMID 20398276, 2010). "The role for intratumoral SOCS1 and SOCS3 proteins as novel therapeutic targets remains deserves further evaluation in pre-clinical studies of melanoma or other malignancies." (PMID 20398276, 2010). "The interferon-responsiveness of SOCS1 and SOCS3-positive 1259 MEL melanoma cells transfected with a vector expressing siRNA constructs targeting SOCS1 or SOCS3 was next investigated." (PMID 20398276, 2010). "Several studies have shown that SOCS proteins including SOCS3 are expressed in tumours including head and neck cancer, gastric carcinoma, chronic myeloid leukemia, melanoma and prostate cancer." (PMID 20553623, 2010). "Over-expression of SOCS1 and SOCS3 proteins in melanoma cell lines led to a significant decrease in the IFN-responsiveness of melanoma cells." (PMID 20398276, 2010). "IFN-α and IFN-γ treatment led to further increases SOCS1 and SOCS3 expression in some human melanoma cell lines." (PMID 20398276, 2010). "Immunoblot analysis revealed an induction of SOCS1 and SOCS3 proteins in some melanoma cell lines following a four hour stimulation with IFN-α (104 U/mL) or IFN-γ (10 ng/mL)." (PMID 20398276, 2010). "The present study demonstrates that SOCS1 and SOCS3 proteins were expressed in a panel of melanoma cell lines from various stages of disease and in melanocytes." (PMID 20398276, 2010). "In support of this argument is another observation that prolonged cultivation of melanoma cells has been reported to lead to an increase in the constitutive expression of SOCS3 transcripts in vitro." (PMID 20398276, 2010). "Similarly to SOCS1, the role of SOCS3 in melanoma appears to be context-dependent, exhibiting both tumor-suppressive and pro-tumorigenic functions." (PMID 38975347, 2024). "For instance, epigenetic silencing of SOCS3 has been observed in malignant human melanoma." (PMID 38975347, 2024).
melanoma (continued). "Factors secreted by these cells downregulated NQO1 and SOCS3 expression in some of the melanomas." (PMID 37894348, 2023). "Factors secreted by these cells upregulated NQO1 and SOCS3 expression in melanoma." (PMID 37894348, 2023). "In view of its role as an endogenous regulator of various signaling pathways including the Janus kinase (JAK)-signal transducer and activator of transcription (STAT) pathway and as an immunosuppressor, we focused on the involvement of SOCS3, if any, in the microglia–melanoma crosstalk." (PMID 37296634, 2023). "To test whether PTPN1 and SOCS3 were required, we treated melanoma cells with SAHA and phosphatase inhibitors for 24 hours." (PMID 33158915, 2020). "On the other hand, constitutive SOCS3 expression has been reported in human melanomas, where it can inhibit responsiveness to IFNs and may contribute to resistance to IFN-treatment." (PMID 29020964, 2017). "As a previous study showed that miR-455-5p inhibits the tumor suppressor gene CPEB1 expression to facilitate melanoma metastasis, we next test whether the targeting of SOCS3 by miR-455-5p is important for NSCLC." (PMID 29383133, 2017). "This study demonstrated that the expression of SOCS3 in melanoma is a disadvantage." (PMID 28228755, 2017). "Basal and interferon-alpha (IFN-α) or interferon-gamma (IFN-γ)-induced expression of SOCS1 and SOCS3 proteins was evaluated by immunoblot analysis in a panel of n = 10 metastatic human melanoma cell lines, in human embryonic melanocytes (HEM), and radial or vertical growth phase melanoma cells." (PMID 20398276, 2010). "Finally, and in agreement with our data, studies conducted by other groups have also shown that basal SOCS3 expression was detectable at the transcript and protein level in the metastatic A375 melanoma cell line." (PMID 20398276, 2010). "We hypothesized that SOCS1 and SOCS3 proteins may down-regulate the biological response of melanoma cells to endogenous or exogenously administered interferons." (PMID 20398276, 2010). "Since we observed that both melanoma-derived soluble factors as well as recombinant IL-6 activate the STAT3/SOCS3 pathway in microglia, we asked if IL-6 is present in the of the melanoma cells and whether microglia regulate the secretion of this cytokine from melanoma." (PMID 37296634, 2023). "Microglia cells exposed to melanoma-derived IL-6 exhibited upregulated levels of STAT3 phosphorylation and SOCS3 expression, which, in turn, promoted melanoma cell viability and metastatic potential." (PMID 37296634, 2023). "In order to identify the melanoma-derived factor(s) that induce STAT3 phosphorylation and SOCS3 upregulation, we fractionated the MCM from the four different melanoma cell lines to extracellular vesicles (EVs) and soluble fraction (SF or MCM depleted of EVs)." (PMID 37296634, 2023). "SOCS3 and RAC3 displayed among the highest hypermethylation peaks in our aggressive melanoma lines (92 and 96%, respectively), with a very high differential methylation score, above 70%, between WM266-4 and WM115 cells." (PMID 36125262, 2022). "Deletion of SOCS3 in T cells and macrophages induced anti-tumor effects in MC38 colon cancer and B16F10 melanoma mouse models." (PMID 34830179, 2021). "Emerging evidence also show an anti-inflammatory function of PF4 in melanoma and multiple myeloma through inhibition of STAT3 and upregulation of SOCS3 mediated mechanisms." (PMID 27223426, 2017). "Our data support a role for SOCS3 as a tumor suppressor gene in HNSCC, which agrees with its proposed role in melanoma, lung and liver cancer." (PMID 23028842, 2012). "To further validate the role of SOCS protein expression in regulating IFN-responsiveness of representative human melanoma cell lines (HT144, 1259 MEL), we employed retroviral constructs that expressed SOCS1 and SOCS3." (PMID 20398276, 2010).